ESR1 (estrogen receptor 1)
Diseases named in the same sentence as ESR1 in open-access papers (continued):
Sharing a sentence is not in itself a finding about the gene and the disease.
COVID-19 (36 papers, 2020 to 2025). A disease caused by infection with severe acute respiratory syndrome coronavirus 2. "ESR1 was shown to be downregulated in AD, which causes its inability to subside neurotoxicity and may lead to a worse prognosis of COVID-19 in AD patients." (PMID 36009328, 2022). "Moreover, ESR1, as the target of the ShenFuHuang formulation in a zebrafish model, was associated with septic syndrome in patients with COVID-19." (PMID 34483900, 2021). "ESR1 is a crucial sex factor that provides a protective umbrella to COVID-19 patients by suppressing the immune and inflammatory responses induced by SARS-CoV-2 infection and protects DM patients by improving glycemic homeostasis." (PMID 36532549, 2022). "In conclusion, estrogen, interacting with ESR1/2 receptors, is an essential sex factor that protects COVID-19 patients from death by inhibiting inflammation and immune response caused by SARS-CoV-2 infection." (PMID 35676404, 2022). "In conclusion, estrogen hormone, interacting with ESR1/2 receptors, is an essential sex factor that protects COVID-19 patients by inhibiting inflammation and immune response caused by SARS-CoV-2 infection." (PMID 34611658, 2021). "A strong signature associated with estrogen receptor 1 (ESR1) was observed, with estrogen having anti-inflammatory properties and believed to be associated with reduced COVID-19 severity in women, and reduced SARS-CoV disease severity in female mice." (PMID 34214142, 2021). "Moreover, medications boosting the down-stream signaling of ESR1/ESR2, or inhibiting the inflammation and immune-associated targets on the signaling network can be potentially effective or synergistic combined with other existing drugs for COVID-19 treatment." (PMID 35676404, 2022). "It was observed that the estrogen receptor alpha gene (ESR1) expression was downregulated in patients with AD and COVID-19 compared to AD patients only." (PMID 36009328, 2022). "All the results indicated that the estrogens, interacting with ESR1/ESR2, are the essential sex factors protecting young female COVID-19 patients." (PMID 35676404, 2022). "Medications perturb the down-stream of ESR1/ESR2 to inhibit the inflammation and immune response can be effective or synergistic combined with other existing drugs for COVID-19 treatment." (PMID 34611658, 2021). "The ‘prevalent’ ‘candidate genes’ (ADAM10, ADAM17, AKT1, CTNNB1, ESR1, FGFR1, PIK3CA) might have the most prominent pathophysiological relevance in COVID-19." (PMID 36229517, 2022).
Uterine leiomyoma (33 papers, 2009 to 2026). The presence of a leiomyoma of the uterus. "Furthermore, this study only suggests the possible association between ESR1 rs2234693 and uterine fibroids and cannot establish causality due to its design." (PMID 36890612, 2023). "CONCLUSIONS: Overall, ESR1 enhanced mitochondrial oxidative phosphorylation by activating the Wnt/β-catenin signaling pathway, driving uterine leiomyoma cell proliferation." (PMID 41530718, 2026). "ESR1 knockdown rat uterine leiomyoma cell model (ELT3) was constructed to evaluate the cell proliferation, ferroptosis, and mitochondrial function changes." (PMID 41530718, 2026). "For ESR1, Western blot and real-time quantitative polymerase chain reaction results showed that it was overexpressed in uterine leiomyomas." (PMID 32608475, 2020). "The uterine leiomyomas that developed in the G12V mice were hypercellular and highly mitotic according to Ki-67 staining and they also expressed ESR1." (PMID 33244099, 2020). "One study demonstrated that hypomethylation of ESR1 in uterine leiomyoma correlates with increased mRNA expression in uterine leiomyoma." (PMID 22428009, 2012). "Using total RNA prepared from our second panel of 26 matched specimens, we confirmed that ESR1, SOX18, CCL5, and PCDH10 but not CALCRL are differentially expressed in uterine leiomyomas or that levels of their expression vary by menstrual phase." (PMID 28637297, 2017).
asthma (32 papers, 2007 to 2026). "Another recent study provided evidence for estrogen effects on allergic sensitization/reactions by showing a relationship between an ER-α gene (ESR1) polymorphism and airway hypersensitivity, and an age-related decline in lung function in females with asthma." (PMID 17366818, 2007). "ESR1 was identified as the gene most closely associated with other genes in asthma." (PMID 37422662, 2023). "This SNP is in LD with rs6934016 located near the ESR1 asthma susceptibility gene." (PMID 27445529, 2016). "Our findings that DBP exerts its toxic effects through ESR1 in both asthma and COPD are of value for further detailed exploration." (PMID 40160461, 2025). "Further evaluations showed that the GRB2 gene in both COPD and MLD and the ESR1 and IRF7 genes in asthma and IPF had the highest association with the other genes, respectively." (PMID 37422662, 2023). "ESR1, one of the asthma candidate genes, is involved in pulmonary inflammation, causing a decline in lung function." (PMID 36105239, 2022). "Sexual differences in asthma also result from gene polimorphisms including sex specific asthma risk loci and thymic stromal lymphopoietin (TLSP) and estrogen receptor alpha (ESR1) gene polimorphisms." (PMID 32102344, 2020). "The five identified target proteins, ESR1, KDR, LTA4H, PDE4D and PPARG, show evidence of involvement in the pathological expression of asthma, with three classified as receptors (ESR1, KDR, PPARG), and two categorized as enzymes (LTA4H, PDE4D) (KEGG, UniProt)." (PMID 32185106, 2020). "ESR1 participates in two primary KEGG asthma pathways: the B-Cell signaling pathway and the JAK-STAT signaling pathway, through the Prolactin signaling pathway (KEGG)." (PMID 32185106, 2020). "HTR2C, CYP1B1, CYP19A1, ESR1, ESR2, PDR, and AR are found to be interrelated to hormonal disorders; ABCC1, NQO1, TIMP1, ADRB2, and ALOX5 are associated with asthma." (PMID 29861771, 2018). "CTSB, on the other hand, may have a similar role to ESR1, which is downregulated in alveolar lavage fluid in severe asthma as well as upregulated in bronchial epithelial cells in COPD." (PMID 40160461, 2025). "ESR1 in asthma regulates the proliferation and remodeling of airway smooth muscle (ASM)." (PMID 37422662, 2023). "The Prolactin signaling pathway, targeted by ESR1, activates pathways involved in the inflammatory response including the KEGG secondary MAPK pathway and PI3K pathway and is also involved in the secondary KEGG asthma NF-κB signaling pathway; with ESR1 again acting downstream (KEGG)." (PMID 32185106, 2020). "Computational molecular docking of DCT compounds identified five proteins (ESR1, KDR, LTA4H, PDE4D and PPARG) mutually targeted by asthma genes and DCT compounds and 155 docking connections associated with cellular pathways involved in the biological mechanisms of asthma." (PMID 32185106, 2020). "As ESR1 acts upstream of the Estrogen signaling pathway, there is potential that targeting this gene may inhibit or reduce the effects of those three secondary asthma pathways." (PMID 32185106, 2020). "Using Gromacs-2022.04, we simulated the molecular dynamics (MD) of a 100 ns protein-ligand complex for EGFR, ALB, MAPK8, ESR1, and SRC, respectively, which are typical core targets for allergic rhinitis and asthma." (PMID 37781715, 2023). "Quercetin, luteolin, linolenic acid, adenosine, kaempferol, etc., were considered the potential core compounds, and PTGS2, ESR1, PTGS1, NOS2, AKT1, etc. were the main potential targets of BSYQ for asthma and IPF therapy." (PMID 35672815, 2022). "Methyl rosmarinate (degree, 8; betweenness centrality, 0.02733; closeness centrality, 0.4715) also shared the same targets (STAT3, PIK3CB, MAPK1, ESR1, SYK, and EGFR) and identical asthma-related signaling pathways with caffeic acid." (PMID 35572723, 2022). "In this study, we constructed the PPI network; IL6, CASP3, EGFR, MAPK8, ESR1, CCND1, and PPARG were found to be the core genes of YPF in treating asthma." (PMID 36105239, 2022).
asthma (continued). "Each of the five identified target proteins, ESR1, KDR, LTA4H, PDE4D and PPARG, have established potential to play significant roles involving both the primary and secondary asthma pathways through many signaling cascade pathways." (PMID 32185106, 2020). "More importantly, miR-221/222 has been reported to target estrogen receptor alpha (ESR1), and miR-221-3p has been shown to regulate IL-6 release from abnormal airway smooth muscle in patients with severe asthma, especially women." (PMID 29739446, 2018). "ESR1 participates and acts upstream in the Estrogen signaling pathway involved in the secondary KEGG asthma PI3K-Akt signaling pathway, Calcium signaling pathway and MAPK signaling pathway; targeting immune genes, regulating cell cycles and cell adhesion molecules (KEGG)." (PMID 32185106, 2020). "However, PPARG and ESR1, as negative regulators, affect the transcription factor signaling pathway by inhibiting NF-κB, and some studies have found to support the potential benefits of PPARG agonists in the treatment of asthma." (PMID 32015750, 2020). "Besides transgelin-2, some targets (i.g., ESR1, EGFR, CASP3, and SRC) may be important for the anti-asthmatic effect of glycyrrhizin, and some signaling pathways (i.g., SRC/EGFR signaling pathway) are also promising research directions for improving asthma." (PMID 37711178, 2023).
invasive carcinoma (32 papers, 2004 to 2026). A carcinoma that is not confined to the epithelium, and has spread to the surrounding stroma. "In keeping with diagnostic anatomo-pathological experience, the relative expression of ERBB2, ESR1, PGR and MKI67 in our study was often higher in DCIS samples than in samples enriched for invasive carcinomas." (PMID 30342538, 2018).
migraine (31 papers, 2006 to 2025). "For example, Xingkai (2021) reported that variants in the ESR1 gene are associated with the development of migraine in Chinese patients." (PMID 41143151, 2025). "Regarding ESR1 and its variant studied in the Indian population, only PvuII showed a significant association with the risk of migraine including both of its clinical subtypes in contrast to XbaI." (PMID 37925562, 2023). "It has been found, that the ACE-DD variant (allele model: OR: 1.37 [1.11–1.69], I2 = 0%/ fixed model), ESR1-PvuII (allele model: OR: 1.47 [1.24–1.74], I2 = 0%/ fixed model) significantly increases the risk of migraine in Indian population." (PMID 37925562, 2023). "In conclusion, this present meta-analysis showed that the ACE-DD variant and ESR1-PvuII showed a significant risk of migraine in the Indian population in contrast to LRP1- rs11172113 which showed a protective role in the respective population." (PMID 37925562, 2023). "Recent research has suggested that the genetic variants of ESR1 gene have a role in the development of migraine." (PMID 35627115, 2022). "In two separate Australian case-control populations, the G594A SNP in exon 8 of ESR1 was positively associated with to migraine." (PMID 35627115, 2022). "Schurks and colleagues reported association between migraine and G594A and C325G polymorphisms of ESR1, which were shown to be dominant and recessive, respectively." (PMID 35627115, 2022). "ESR1 rs2228480 (594G>A) carries a higher risk for migraine in an Australian population, whereas ESR1 rs2234693 is associated with migraine susceptibility in a Chinese population." (PMID 29890676, 2018). "This study included 8 published articles following criteria for reviewing genetic association studies and identified the ESR1 G594A and C325G SNPs as contributors to migraine with pooled Odds Ratios yielding greater statistical significance." (PMID 24403849, 2013). "The ESR1 C325G locus was genotyped and the ESR1 gene emerged as the strongest candidate associated with migraine, a result which is consistent with previous association studies." (PMID 24403849, 2013). "In other words, we report that the effect of ESR1 polymorphisms on migraine risk diminish from amino to carboxy terminal." (PMID 22511967, 2012). "Four polymorphisms of ESR1 gene were explored for association with migraine and its clinical subgroups." (PMID 22511967, 2012). "Significant interactions were observed for CYP19A1 rs10046 with ESR2 rs1271572, ESR1 rs2234693 and ESR1 rs9340799 polymorphisms conferring risk for migraine susceptibility." (PMID 22511967, 2012). "Out of four ESR1 polymorphisms, only rs2234693 variant allele was significantly associated in migraine with aura." (PMID 22511967, 2012). "In conclusion, we report the significant association of CYP19A1 3′UTR and ESR1 rs2234693 polymorphism with migraine risk." (PMID 22511967, 2012). "Risk variants and haplotypes in dopamine metabolism genes, DBH, DDC, MAOA, and SLC6A3, are reported to influence migraine risk, as are variants in the oestrogen receptor gene, ESR1." (PMID 22030984, 2011). "To investigate the potential role of ESR1 in migraine we conducted an association study of the ESR1 G594A polymorphism (rs2228480) and migraine in two independent case-control groups." (PMID 16504171, 2006). "The estrogen receptor 1 (ESR1) gene is a potential migraine candidate due to the well-known hormonal influence on migraine susceptibility." (PMID 16504171, 2006). "Moreover, epigenetic alterations in MTHFR and ESR1 genes have been shown to be relevant to elevated homocysteine plasma levels and reduced mRNA content of estrogen receptor alpha (ERα), respectively, both of which are associated with migraine pathology." (PMID 40391079, 2025).
migraine (continued). "Overall, the results of this meta-analysis indicated that the ACE-DD variant and the ESR1-PvuII were associated with an increased risk of migraine in the Indian community, while the LRP1-rs11172113 variant was associated with protection from migraine in this population." (PMID 37925562, 2023). "Concerning ESR1-PvuII, a significant association has been found where the allele (OR: 1.47 [1.24–1.74], I2 = 0%), dominant (OR: 1.66 [1.30–2.12], I2 = 0%), and recessive model (OR: 1.91 [1.31–2.77], I2 = 0%) significantly increase the risk of migraine." (PMID 37925562, 2023). "Moreover, a combined study of both hormonal genes revealed that the insertion of the Alu allele in intron 7 (PROGINS) combined with the 594A ESR1 allele increased the risk of migraine by 3.2 fold." (PMID 35627115, 2022). "In addition, ESR1 rs1801132 (325C>G) is positively associated with migraine in a Spanish population." (PMID 29890676, 2018). "Many studies in migraine have focused on ESR1 gene polymorphisms." (PMID 22511967, 2012). "However, among six studies on ESR1 rs1801132 polymorphism, only two studies reported significant associations with migraine." (PMID 22511967, 2012). "We have previously reported a role for the ESR1 G594A polymorphism in migraine susceptibility." (PMID 16504171, 2006). "There have been convincing replications of many genetic associations with potential migraine genes, such as methylene-tetrahydrofolate reductase (MTHFR), insulin receptor (INSR) and estrogen receptor 1 (ESR1)." (PMID 33083518, 2020). "The hormone-regulated etiology of migraine is supported by the estrogen receptor 1 (ESR1) genetic variability." (PMID 29890676, 2018). "In summary the synonymous polymorphisms 325C>G (exon 4) and 594G>A (exon 8) have been investigated the most for ESR1 and migraine." (PMID 24403849, 2013). "The gene encoding estrogen receptor alpha, (ESR1) localized in 6q25.1 locus is the most widely studied hormonal pathway gene in migraine." (PMID 22511967, 2012). "Thus, we considered that variation in the ESR1 gene may confer increased migraine risk." (PMID 16504171, 2006). "We have previously reported an association between the estrogen receptor 1 (ESR1) gene exon 8 G594A polymorphism and migraine susceptibility in two independent Australian cohorts." (PMID 16504171, 2006). "ESR1 rs2234693 is a risk factor for migraine without aura, female migraine, and menstrual-associated migraine." (PMID 41143151, 2025). "In the migraine with aura subgroup, only 1 (TNF-α/rs1800629) and 3 (MTHFR/rs1801133, ESR1/rs1801132 and TNF-α/rs1800629) genetic variants was noteworthy in FPRP at the prior probability of 0.05 with a statistical power to detect an OR of 1.2 and 1.5, respectively." (PMID 32046629, 2020). "Interestingly when the original authors analyzed the interaction of both hormonal genes together (ESR1 594A allele and PROGINS variant) they identified a synergistic effect whereby migraine risk was increased 3.2 times." (PMID 24403849, 2013). "Polymorphisms in ESR1 and PGR may increase migraine prevalence only in some populations demonstrating an ethnic-specific effect." (PMID 24403849, 2013). "Pooled analyses of the available studies suggest that the estrogen receptor-1 gene (ESR-1) 594 G>A and 325 C>G polymorphisms can modify the risk for migraine, a finding that does not differ between MA and MO." (PMID 22072275, 2012). "Moreover, molecular docking results demonstrated that these core components have a strong affinity with multiple target proteins such as PTGS2, PPARG, BCL2, CASP3, TNF, and ESR1, suggesting that ginkgo seeds exert their therapeutic effects on migraines through multiple targets and pathways." (PMID 41009787, 2025). "While links between estrogen receptor genes (ESR1, ESR2) and migraine have been suggested, larger-scale studies have yet to fully validate these associations." (PMID 40149800, 2025).
migraine (continued). "Interesting overlapping candidate genes for migraine and glucose-related traits are MTHFR, INSR, TNF, ESR1, NOS3, and PON1." (PMID 35627115, 2022). "This study was aimed at investigating genetic variants that are potentially related to MM, specifically undertaking genotyping and mRNA expression analysis of the ESR1, PGR, SYNE1 and TNF genes in MM cases and non-migraine controls." (PMID 25315199, 2014). "Additionally, methylenetetrahydrofolate reductase (MTHFR), estrogen receptor 1 (ESR1), and nitric oxide synthase 1 (NOS1), along with their methylation patterns, are considered important genes involved in migraine pathogenesis." (PMID 40391079, 2025). "According to one research, estrogen receptor 1 (ESR1) and estrogen receptor 2 (ESR2) may contribute to the hereditary basis of migraine." (PMID 37123778, 2023). "The role of E2 as an epigenetic modulator in the methylation of genes involved in migraine pathophysiology including ESR1 was investigated without demonstrating a significant effect." (PMID 35456034, 2022). "Genetic studies of hormonal genes have focused on the estrogen receptor (ESR1) and the progesterone receptor (PGR) genes, a logical choice based on fluctuating hormones of the ovarian cycle which many women recognize as triggers for their migraine." (PMID 24403849, 2013). "In contrast, the ESR-1 Pvu II C>T polymorphism and the progesterone receptor (PGR) PROGINS insert polymorphism do not appear to be associated with migraine." (PMID 22072275, 2012).